OR51Q1 (olfactory receptor family 51 subfamily Q member 1)
Description:
Odorant receptor.
Tractability: Antibody: UniProt places it where antibodies can reach, with medium confidence; UniProt predicts a signal peptide or a membrane-spanning region; its Gene Ontology location is reachable by antibodies, with medium confidence.
Gene: Protein-coding gene on chromosome 11 (5,422,111 to 5,423,206, forward strand). Ensembl gene ENSG00000167360.
Subcellular location: Cell membrane
Pathways (Reactome):
Sensory Perception: Expression and translocation of olfactory receptors
Gene Ontology:
Molecular function: olfactory receptor activity; G protein-coupled receptor activity; signaling receptor activity
Biological process: cellular response to lipid; detection of chemical stimulus involved in sensory perception of smell; G protein-coupled receptor signaling pathway; system process
Cellular component: plasma membrane; membrane
Genetic constraint (gnomAD): Loss-of-function variants: 1 observed, 0.34 expected, observed/expected ratio (o/e) 2.96. That is too few expected variants to judge how well the gene tolerates losing a copy. Missense variants: 499 observed, 414.48 expected, observed/expected ratio (o/e) 1.2, 90% interval 1.12 to 1.3. Synonymous variants: 187 observed, 158.4 expected, observed/expected ratio (o/e) 1.18, 90% interval 1.05 to 1.33.
Homologues: Orthologues: chimpanzee OR51Q1 (96% identical), rat Or51q1e (84% identical), mouse Or51q1 (84% identical), rat Or51q1 (83% identical), mouse Or51q1c (82% identical), rat Or51q1d (82% identical), rabbit OR51Q1 (81% identical), pig OR51Q1 (77% identical), guinea pig OR51Q1 (74% identical). Paralogues in human: OR51G2 (54% identical), OR51A4 (50% identical), OR51L1 (50% identical), OR51A2 (50% identical), OR51A7 (50% identical), OR51V1 (50% identical), OR51G1 (49% identical), OR51I2 (49% identical), OR51F2 (47% identical), OR51M1 (47% identical), OR51I1 (46% identical), OR51C1 (46% identical), and 39 more.
Diseases named in the same sentence as OR51Q1 in open-access papers:
OR51Q1 is named in the same sentence as 4 diseases in open-access papers, as found by Europe PMC text mining. Sharing a sentence is not in itself a finding about the gene and the disease. The quoted sentences say what the papers report.
type 2 diabetes (1 paper, 2017). "In summary, we identified a novel metabolite locus (MOGAT2) in single variant analyses and four genes (GFRAL, BIN1, TFRC, OR51Q1) within gene-based tests and could show that two previously known mGWAS loci (FADS1 and REV3L) might be relevant for the risk of type 2 diabetes." (PMID 28729637, 2017).
OR51Q1 also shares sentences with these, for which no sentence is quoted: cancer (1 paper); pancreatic adenocarcinoma (1); pancreatic cancer (1).